PDGFA-DT (PDGFA divergent transcript)
Synonyms: HRAT92
Gene: Long non-coding RNA gene on chromosome 7 (519,288 to 533,282, forward strand). Ensembl gene ENSG00000223855.
Diseases named in the same sentence as PDGFA-DT in open-access papers:
PDGFA-DT is named in the same sentence as 1 disease in open-access papers, as found by Europe PMC text mining. Sharing a sentence is not in itself a finding about the gene and the disease.
PDGFA-DT shares sentences with these, for which no sentence is quoted: low grade glioma (1 paper).